EPX (eosinophil peroxidase)
Diseases named in the same sentence as EPX in open-access papers (continued):
Sharing a sentence is not in itself a finding about the gene and the disease.
infection (9 papers, 2013 to 2025). The state of being infected such as from the introduction of a foreign agent such as serum, vaccine, antigenic substance or organism. "From the host perspective, temporal regulation of known immune-associated proteins, including eosinophil peroxidase and lipocalin-2, along with suppression of lipoproteins, demonstrated infection- and time-dependent host remodeling." (PMID 41061967, 2025). "Furthermore, EPX could regulate the inflammatory process to control the infection." (PMID 34504189, 2021). "For that purpose, eosinophils and neutrophils contain specific granules containing protoporphyrin-type proteins such as eosinophil peroxidase (EPO) and myeloperoxidase (MPO), respectively, which contribute directly to their anti-infection activity." (PMID 32906767, 2020). "Qualitatively, we observed Siglec-F+ cells in the lungs of TIV-vaccinated NC99-challenged breakthrough infection mice, but in the absence of cell-free eosinophil peroxidase (EPX)." (PMID 41190814, 2025). "The upregulation of the EPX may be a consequence of FHS, since a possible infection could pressure the bone structure, impairing the blood supply to the affected area, developing necrosis." (PMID 34504189, 2021). "To investigate whether eosinophils are involved in both protection and pathology during filarial nematode infection, we explored the role of eosinophils and their granule proteins, eosinophil peroxidase (EPO) and major basic protein-1 (MBP-1), during infection with Brugia malayi microfilariae." (PMID 24626328, 2014).
inflammation (5 papers, 2016 to 2024). Aberrant reaction of the microcirculation characterized by movement of fluid and leukocytes from the blood into extravascular tissues. "We show that both EPX and Properdin, markers of eosinophilic airway inflammation, are higher in females compared to males in the mouse model, which corroborates evidence that eosinophilic airway inflammation is higher in females compared to males." (PMID 35837410, 2022). "IL4 and IL5RA are well-characterized cytokines responsible for Th2 cell differentiation and effector function, ADAM19 is involved in airway and vasculature remodeling, and PRG2 and EPX are both eosinophil-related proteins that play key roles in eosinophil-related airway inflammation." (PMID 29692868, 2018).
Bacterial infections (1 paper, 2024). "Bacterial infections can activate eosinophil peroxidase and the myeloperoxidases in neutrophils and monocytes." (PMID 39767168, 2024).
infectious disease (1 paper, 2017). A disorder directly resulting from the presence and activity of a microbial, viral, or parasitic agent in humans. "Particularly prevalent and relatively high expression of eosinophil peroxidase suggests the influence of infectious diseases." (PMID 28680659, 2017).
EPX also shares sentences with these, for which no sentence is quoted: cancer (3 papers); Allergy (2); urticaria (2); autoimmune disease (1); autoimmune hepatitis (1); Autoimmunity (1); brain infarction (1); breast carcinoma (1); colorectal cancer (1); emphysema (1); eosinophilic gastroenteritis (1); food allergy (1); Hodgkin's disease (1); influenza (1); leukopenia (1); liver (1); myocardial infarction (1); nasal obstruction (1); nasal polyps (1); neurodegenerative disease (1); onchocerciasis (1); osteoarthritis (1); periodontal disease (1); rheumatoid arthritis (1); schistosomiasis (1); sickle cell disease (1); Ss (1); trichinellosis (1); type I hypersensitivity reaction (1); ulcerative colitis (1).